KRAS (KRas proto-oncogene, GTPase)
Diseases named in the same sentence as KRAS in open-access papers (continued):
Sharing a sentence is not in itself a finding about the gene and the disease.
tumor (continued). "Preclinical studies have shown that AMG510 can inhibit almost all measurable ERK phosphorylations, a key downstream effector of KRAS, thereby enabling KRAS G12C mutant tumour mice to achieve long-lasting tumour regression." (PMID 34012925, 2021). "Wild-type KRAS shows a tumor growth-inhibiting function in KRAS-mutant cancer by preventing cellular transformation and decreasing the tumor burden in several malignancies." (PMID 33658393, 2021). "Sotorasib inhibits MAPK signaling and tumor growth in KRAS G12C cell lines and patient-derived xenograft models." (PMID 33917906, 2021). "Phase I clinical trials show that SHP2 inhibitors are tolerated well and reduced tumor volume in a subset of KRas G12C mutant NSCLC when combined with KRas inhibition." (PMID 34680208, 2021). "In turn, KRAS-reprogrammed macrophages were shown to not only promote tumor progression but also induce the resistance of tumor cells to cetuximab therapy." (PMID 33833221, 2021). "Further, it has been demonstrated that oncogenic KRAS can mediate activation of canonical Wnt signaling to support tumor growth by promoting macropinocytosis, along with the induction of metabolic reprogramming (Warburg effect)." (PMID 33691728, 2021). "Conversely, specific SOS2 functions, including a critical role in regulation of the RAS–PI3K/AKT signaling axis in keratinocytes and KRAS-driven tumor lines or in control of epidermal stem cell homeostasis, were also reported." (PMID 34205562, 2021). "Approximately 93% of pancreatic adenocarcinomas harbor mutant KRAS oncogene, which drives tumor pathogenesis." (PMID 34948200, 2021). "Arginylglycylaspartic acid exosomes containing KRAS siRNAs delivered to A549 tumors in vivo resulted in KRAS knockdown and subsequent tumor suppression." (PMID 34677212, 2021). "SNORD50A/B has been demonstrated to be highly deleted in different types of cancer and exerts its tumor suppressor function by inhibiting the activity of KRAS oncoproteins." (PMID 33742136, 2021). "In mutant KRAS-derived EVs authors showed enrichment of tumor-suppressive miR-100 while the oncomiR miR-10b was preferentially secreted in EVs derived from wild type KRAS cell line; these data demonstrate a key role for KRAS in orchestrating RNA trafficking." (PMID 34943863, 2021). "Namely, direct targeting of mutant KRAS variants using various CRISPR systems resulted in significant decrease in cell viability and proliferation in vitro, as well as tumor growth inhibition in vivo." (PMID 34781949, 2021). "MRTX849 has tumor regression in KRAS G12C positive cell lines and patient-derived xenograft models from multiple tumor types." (PMID 34830757, 2021). "We found that KRAS‐mt tumors display lower expression of genes related to the tumor stroma and remodeling of the extracellular matrix." (PMID 33817986, 2021). "We demonstrated that inhibition of ERAD, a downstream cellular process triggered by UPR, enhanced FTS efficacy, suggesting that FTS likely induces UPR in the KRAS-driven PDAC tumor cells." (PMID 33676427, 2021). "KRAS mutations are associated with more aggressive tumor phenotypes and poor prognosis in CRC patients in comparison to those with wild type-KRAS." (PMID 34769370, 2021). "To explore the prevalence of KRAS gene mutations in the Saudi population, we collected 80 CRC tumor tissues and sequenced the KRAS gene using automated sequencing technologies." (PMID 34369256, 2021). "In the early phase, KRAS mutation, CN loss of 3p21.1, and upregulation of EMT facilitate dissemination from primary tumor." (PMID 33397441, 2021). "Of note, genomic screenings have enabled the discovery of synthetic lethal partners to inhibit tumor growth in KRAS-mutant cancer cells." (PMID 34607583, 2021).
tumor (continued). "On the other hand, it is demonstrated that inhibition of HSP90 (by shRNA or small molecules) led to a decrease in protein content of STK33 and reduction of viability in vitro and tumor growth rate in vivo for KRAS mutant CRC cell lines." (PMID 34955846, 2021). "In a KRAS-mutated murine PDAC cell model, tumor-intrinsic CXCL1 expression alone determines the quantitative and qualitative features of infiltrative CD8+ T cells and hence response to checkpoint immunotherapy." (PMID 34771644, 2021). "Mechanistically, this study identified BRAF and MYC as key downstream regulators of KRAS-driven tumor immune suppression for PDA maintenance." (PMID 34290984, 2021). "The degree to which tumor sidedness influenced physicians’ first-line targeted therapy choice for patients with KRAS wildtype varied across geographic regions." (PMID 34199694, 2021). "A study investigating the sensitivity of cetuximab in colorectal cancer PDX models found tumour responses exclusively in KRAS wild-type." (PMID 34321074, 2021). "Induced expression of miR-23b-27b-24-1 increased drug sensitivity and reduced invasiveness of NSCLC cells by silencing gene members of the oncogenic NF-κB and KRAS pathways, also identifying a tumor suppressive role for this cluster." (PMID 33572600, 2021). "KRAS—a key downstream GTPase of several growth factor receptors and member of the RAS family of GTPases—is frequently mutated in multiple tumor entities including lung adenocarcinoma (33%), colorectal carcinoma (42%), and PDAC (93%)." (PMID 34496946, 2021). "KRAS status was evaluated on four different areas of the original tumour, including the mirror sample used for PDE culture and a lymph node metastasis, with the same result (no mutation)." (PMID 34572922, 2021). "We then cocultured cetuximab sensitive SW48 cells with the KRAS-Mφ and challenged the tumor cells with cetuximab." (PMID 33833221, 2021). "Mechanistically, mutationally activated KRAS stabilizes HIF-1α, which drives the production of CSF2 and lactate in tumor cells." (PMID 33833221, 2021). "In a subset of patients, we compared the mutation status of KRAS and BRAF genes in the primary tumor and serum samples." (PMID 33669856, 2021). "Combining the KRAS G12C inhibitor AMG-510 and anti-PD-1 increased CD8+ TME infiltrates, causing marked tumour regression in vivo compared to either treatment alone." (PMID 34944851, 2021). "We found that a subset of genes, for instance activated Braf and Akt1, did accelerate KRAS KO tumor formation in nude mice." (PMID 33674596, 2021). "This work pointed to KRAS dimerization as a potential therapeutic target, since impairing KRAS dimerization leads to tumor growth reduction and to an increase in MEK inhibitor sensitivity." (PMID 34680951, 2021). "PLEXIND1 plays a pro-tumorigenic role in KRASmut cells, while it acts as a tumor suppressor in KRASwt cells, suggesting a correlation between the genetic status of KRAS and role of PLEXIND1 in the PDAC cells." (PMID 34439202, 2021). "Our results are consistent with markedly greater potency and efficacy using the combined CA170/KRAS vaccine treatment in inhibiting tumor growth versus the KRAS vaccine alone." (PMID 34302042, 2021). "One group found that by combining Avasimibe with a KRAS multi-peptide vaccine in prophylactic mouse models, a significant decrease in tumour volume was seen compared to monotherapies, with an increase in CD8+ T cell levels in the TME." (PMID 34276688, 2021). "Epigenetic regulators of tumor immunity were screened with the use of CRISPR technology in in vivo models of KRAS-driven LUAD." (PMID 34781949, 2021). "In our study, we showed that RGS, a reported small molecular RAS signaling disruptor, had a selective anti-tumor effect in KRAS-mutant CRC." (PMID 34347396, 2021).
tumor (continued). "The impact of tumor-cell KRAS signaling on various cell types in the TME has been well covered by several reviews." (PMID 34771644, 2021). "Another study of 106 primary human CRC tumor samples and 59 PDXs aimed to identify a molecular signature predictive of cetuximab sensitivity in KRAS wild-type CRC." (PMID 34546978, 2021). "Our data indicate that the ability of mutant KRAS to modulate tumor immunity appears to be an essential component of its oncogenicity." (PMID 33674596, 2021). "While KRAS is a driver oncogene, tumor cells can acquire mutant KRAS independency by activating pathways that functionally substitute for mutant KRAS." (PMID 34680229, 2021). "The high-risk group had a higher tumor mutational burden (TMB) (p < 0.05), with significantly higher mutation frequencies in KRAS and ADAMTS12 (p < 0.05)." (PMID 35047000, 2021). "Among gene pairs tested, the combined expression of BrafV600E and Myr-Akt1 partially restored KRAS KO tumor formation in wild-type mice." (PMID 33674596, 2021). "AZD4785 selectively inhibits the proliferation of mutant KRAS-driven tumor cells in vitro or in xenograft models." (PMID 34607583, 2021). "A variety of laboratory methods are available for the detection of KRAS mutations in biological samples, including formalin-fixed paraffin-embedded (FFPE) tissues, fresh tumor tissues, fine-needle aspiration (FNA) materials and cytology and body fluids." (PMID 34742312, 2021). "The aggregation of mitochondrial KRAS-G12V protein also favors tumor cell growth through metabolic effects." (PMID 34607583, 2021). "Coculture with KRAS-Mφ significantly enhanced the tumor growth capacity, as determined by soft agar colony formation and plate colony formation." (PMID 33833221, 2021). "For the 4T1 tumors, EMT and KRAS pathways were negatively enriched following pFUS compared to controls over the initial 12 h, which would be consistent with slowing tumor growth." (PMID 33801627, 2021). "The mutation of ctKRAS G12D DNA from the buffy coat was statistically significant from the KRAS status of the primary tumor, which was defined by IHC analysis." (PMID 34442609, 2021). "Instead, our work provided an alternative solution, altering the phenotypic state of mitochondria driven by KRAS through Drp1, which in turn suppresses tumor growth through modulating levels of defective mitochondria and limiting OXPHOS capability in PDAC." (PMID 34564443, 2021). "KRAS status evaluation was previously performed on the tumour tissue, then in plasma; the information on the tissue KRAS status was available for the totality of the ctDNA-assessable patients (n = 106)." (PMID 33923563, 2021). "The use of combination SHP2 and KRAS G12C inhibition have been shown to decrease tumor growth in in vivo models compared to monotherapy alone." (PMID 34845311, 2021).
tumor (continued). "Recent reports have indicated that miR-193a-3P can inhibit tumour progression by targeting KRas in lung cancer." (PMID 33865381, 2021). "The discovery of ccfDNA originating from a solid tumor (i.e., circulating tumor DNA, ctDNA) was first achieved in 1994 using PCR-based methods to target a specific mutagenic locus – the KRAS G12 codon." (PMID 34298235, 2021). "It works by irreversibly and selectively binding to KRAS G12C in its inactive state, blocking its signaling to other cells, thus preventing tumor cell growth and proliferation, leading to cancer cell death." (PMID 34944853, 2021). "Due to the strong autophagy dependence of KRAS mutant tumours, their inhibitors, such as chloroquine, have been used for treating cancer in the clinic." (PMID 33925206, 2021). "Defining KRAS KO tumor cell types was more intricate than those of KRAS intact tumors owing to massive changes in gene expression." (PMID 33674596, 2021). "Genetic analysis of primary tumour revealed KRAS Q61K, wild-type IDH1/2, H3F3A, HIST1H3B and TERT promoter, and no MGMT promoter hypermethylation." (PMID 34525976, 2021). "Upon disruption of mutant KRAS using Cas9 and sgRNA, a remarkable reduction in the tumor size (7, twofold) in KRAS mutant mice was determined." (PMID 34781949, 2021). "In order to check for this possibility, we calculated the ratio between the measured WT DNA in BRAF assay and the mean value of all measured WT amounts of DNA in KRAS assays in tumor samples." (PMID 33669856, 2021). "Another strategy to disrupt and prevent RAS function is through interference with the binding of phosphodiesterase 6 delta (PDEδ) to KRAS, thus hindering tumor development." (PMID 34638560, 2021). "On the other hand, anti-EGFR agents improved PFS in KRAS wild type tumor affected patients: cetuximab in combination with FOLFIRI and panitumumab with FOLFOX led to an increase of PFS up to 9,9 and 10 months, respectively." (PMID 33613849, 2021). "There are some promising in vitro results showing that inhibitors against prenyl-binding protein PDEδ, which prevents KRAS from localizing to the plasma membrane, inhibit the growth of KRAS mutant tumor cell lines." (PMID 33801965, 2021). "MiR-143 has been reported as a tumor suppressor that targets a large array of cancer-related signaling pathways, such as KRAS pathway, ERK signaling, glycolysis and matrix metalloproteinases." (PMID 34170852, 2021). "For instance, eIF2α‐P post‐translationally regulates PD‐L1 expression in MYC transgenic/KRAS mutant murine tumor." (PMID 34698427, 2021). "Questions immediately arise as to what types of various anti-tumour therapies can be used in KRAS mutant cancer cells." (PMID 33925206, 2021). "A similar kinome adaptive response has been observed in KRAS G12C-mutant tumor cells using irreversible cysteine reactive KRAS G12 inhibitors, which specifically interact with the mutant cysteine on the 12th residue of KRAS to inactivate the kinase activity." (PMID 34461089, 2021). "Instead, ARS-1620, a covalent compound with high potency and selectivity for KRAS G12C, have shown rapid and sustained tumor regression in vivo." (PMID 35004317, 2021). "On a subset of CRC patients, we compared the mutation status on KRAS (G12A, G12D, G12V, G13D) and BRAF (V600E) genes in the primary tumor and cfDNA isolated from the serum." (PMID 33669856, 2021).
tumor (continued). "We found that KRAS mutant tumors display lower expression of genes related to the tumor stroma and remodeling of the extracellular matrix." (PMID 33817986, 2021). "Thought to act as a downstream mediator of numerous oncogenic drivers, such as KRAS, EGFR, or mutated PTEN, PI3K-AKT-mTOR pathway signalling controls tumour development and regulates the cellular composition of the TME29,35,36." (PMID 34381028, 2021). "Polysome profiling of KRAS G12D tumor cells indicated that p-eIF2α inhibits DUSP6 at the translational level." (PMID 34330898, 2021). "In this case, no GLUT1 expression is observed; furthermore, autophagy is also inhibited that can result in a real win situation because of the strong autophagy dependence of KRAS mutant tumours." (PMID 33925206, 2021). "The current clinical trials have broadened eligibility to include circulating tumor DNA for some KRAS G12C trials." (PMID 34845311, 2021). "The similar results of those all studies together were revealed in this analyze by using qPCR, including the relationship between F. nucleatum and tumor side, TNM Stage, T stage, N stage, KRAS mutation, OS and DFS in CRC." (PMID 33613745, 2021). "KRAS and BRAF non-V600E mutations are more frequent in smokers and have been reported as correlated with an immunogenic tumor microenvironment." (PMID 34359727, 2021). "We previously reported that mutant KRAS exosomes derived from CRC cells can alter the metabolic state of the tumour microenvironment." (PMID 34887515, 2021). "Considering the role of the microenvironment in influencing tumor initiation and promotion, the immune tumor niche of KRAS mutant tumors has been deeply explored and characterized for its unique immunosuppressive skewing." (PMID 33777798, 2021). "Previous studies have shown that PTPN14 is a tumor suppressor that regulates Yap/Hippo signaling, and Yap can be a major effector of mutant KRAS during tumor progression." (PMID 34815476, 2021). "The preclinical studies have demonstrated that it selectively inhibits the KRAS G12D mutant forms, binds both the active and inactive forms and significant dose dependent tumor regression was noted in the animal models." (PMID 34944853, 2021). "Targeting of the mutant KRAS using this system, resulted in inhibition of cell survival and tumorigenicity in vitro, as well as a decrease in tumor volume in xenografts." (PMID 34781949, 2021). "The tumour-associated macrophages (TAMs) provided cancer cells with trophic support, including TGF-β, to enable oncogenic KRAS bypass in a Smad4-dependent manner." (PMID 33671588, 2021). "Treatment with AMG 510 regresses in KRAS G12C mouse xenografts and induces pro-inflammatory tumor microenvironment." (PMID 34830757, 2021). "The objective of the study is to investigate the effect on pathological tumor response in resectable tumors and to observe objective tumor response in KRAS or BRAF mutant metastatic tumors (NCT03146962)." (PMID 34717701, 2021). "The LVI status was significantly associated with pT stage, degree of differentiation, tumor stage, serum CEA and CA19-9 levels, perineural invasion, tumor budding, and KRAS status." (PMID 33866973, 2021). "Given the significant dependence of KRAS mutant tumor cell growth on glutamine and leucine supply, it is reasonable to expect that these cells upregulate specific AATs to meet this requirement." (PMID 34003553, 2021). "In 35 tumor samples extraction of mRNA was successful and all samples were included in the analysis of relative KRAS and HRAS mRNA expression levels using qRT-PCR." (PMID 33549031, 2021). "We further assessed the effects of ISR inhibition on mouse KRAS G12D tumor growth in syngeneic mice." (PMID 34330898, 2021). "Survival in wild-type KRAS tumours with PCI 1–10 was 71% and with PCI 11–20 was 26%, while in mutant-type KRAS tumours, survival was 41% and 4%, respectively (P=0.025)." (PMID 34557315, 2021).